FOXP3 (forkhead box P3)
Diseases named in the same sentence as FOXP3 in open-access papers (continued):
Sharing a sentence is not in itself a finding about the gene and the disease.
breast carcinoma (continued). "In contrast, CD8 + T-cell counts (p = 0.039), FOXP3+ T-cell counts (p = 0.004), and FOXP3+/CD8+ T-cell ratio (p = 0.007) were significantly higher in non-responders than in responders as for post-treatment breast cancers." (PMID 37115435, 2023). "Moreover, analysis of clinical specimens showed a significant negative correlation between the expression levels of FOXP3 and MTA1 in breast cancer." (PMID 34307133, 2021). "As a result, it prevents the tBreg-induced conversion of FoxP3+ Tregs cells, which exert a powerful immunosuppressive character in the tumor microenvironment (TME) and play a crucial role in breast cancer metastasis while remaining non-toxic to effector immune cells." (PMID 33572626, 2021). "Previous studies confirmed that in breast cancer, tumor-induced Bregs promote tumor metastasis by converting dormant CD4+CD25− T cells into CD4+CD25+Foxp3+ Tregs, while in the absence of tumor-induced Bregs, the conversion of Tregs was significantly reduced and tumor metastasis was blocked." (PMID 32456622, 2020). "Thus, we propose that FOXP3 and miR-155 co-operate to down regulate ZEB2, but not ZEB1, in breast cancer cells." (PMID 29963231, 2018). "A simple ratio between FOXP3+ and CD8+ TILs may not be an appropriate universal prognostic indicator, across biologically different breast cancer subtypes." (PMID 25193543, 2014). "The aim of this study was to investigate the prognostic and predictive role of FoxP3 + regulatory TILs, CD8 + cytotoxic TILs in the tumor margin (CD8 + mTILs), and the ratios of CD8 + mTILs with FoxP3 + TILs and TAMs in a material of 139 non-metastatic HER2 + breast cancer patients." (PMID 37428418, 2023). "Finally, analysis of the breast samples from the The Cancer Genome Atlas data sets revealed a strong association of CCR8 mRNA amounts normalized to FOXP3, but not FOXP3 mRNA amounts alone, with poor prognosis, suggesting a detrimental role for CCR8‐expressing Treg cells in breast cancer progression." (PMID 31032905, 2019). "Thus, while maternal obesity does not increase FOXP3 levels in the offspring’s mammary tumors, upregulation of Tgfβ1 and VEGFR2 suggests that maternal HFD may promote immunosuppression in TAM-treated offspring’s mammary tumors." (PMID 32580156, 2020).
colitis (430 papers, 2008 to 2025). Inflammation of the colon. "The results from this study demonstrated that maternal mice exhibited significant resistance to colitis, which was associated with an increased expression of Foxp3 following Emu infection." (PMID 40713878, 2025). "Induction of colitis was associated with an increase in FoxP3 and CD25 in the distal colon of control mice, suggesting T-Reg recruitment." (PMID 40723233, 2025). "Conversely, Gpr15 deficiency in the DSS-induced colitis group under the same conditions significantly reduced the correlation with Foxp3 and Treg cells." (PMID 40957881, 2025). "We isolated lymphocytes from the livers of these mice and found increased frequencies of Foxp3+ Treg in Mdr2-deficient mice upon acute DSS colitis induction and comparable frequencies of IFNγ+ and IL-17A+ CD4+ T cells." (PMID 38510236, 2024). "Tr1 cells prevent colitis in adoptive transfer models, and pathogenic colitis-inducing Th17 cells are suppressed by both Foxp3+ and Foxp3- IL10-producing CD4+ T-cells." (PMID 37654482, 2023). "RyR2 deficiency rendered the CD4+ T cell pool immune suppressive and caused it to behave in the same manner as Foxp3+ Tregs in viral infection, asthma, hypersensitivity, colitis, and tumor development." (PMID 38099494, 2023). "Development of colitis in IL-10KO mice is driven by expansion of Th1 and Th17 cells and has historically been attributed to the loss of IL-10 derived from Foxp3+ intestinal Tregs." (PMID 37314833, 2023). "It has been reported that NR4A2-deficient T cells inhibit Foxp3 expression, leading to an abnormal induction of Th1 cells and aggravation of colitis." (PMID 38006062, 2023). "In an experimental model of colitis, increases in FOXP3+ Treg lymphocytes were associated with preservation of intestinal mucosal integrity and an anti-inflammatory response." (PMID 37859769, 2023). "FoxP3+CD25+ Tregs have been conclusively shown to suppress mucosal inflammation associated with murine colitis." (PMID 34983695, 2022). "The presence of RORγt+FoxP3+ Treg cells is crucial, and it reduces the risk of colitis and colorectal cancer." (PMID 35626725, 2022). "Mice that are deficient in RORγt+FoxP3+ Tregs develop a severer and more lethal type of oxazolone-induced colitis, which is a model of ulcerative colitis." (PMID 35626725, 2022). "A recent study reported that RORγt+ Foxp3+ Treg cells sustain growth of colitis-associated colorectal cancer." (PMID 34512629, 2021). "DSS-induced colitis was associated with increased percentages of Foxp3+CD4+Treg cells in cLP in both WT mice and Lgals1−/− mice with respect to their control non-inflamed counterparts." (PMID 34262567, 2021). "Preclinical studies also have demonstrated that the therapeutic effect of MenSCs on the course of experimental murine colitis is associated with significantly higher level of CD4+CD25+FOXP3+ Treg cells." (PMID 33554005, 2021). "This ICOS mediated sustenance is important as, although ICOS-deficient Treg cells are equally suppressive as wildtype Treg cells in adoptive transfer colitis they eventually cannot prevent mortality in Foxp3 deficient mice." (PMID 34421921, 2021). "In this study, the authors used DNBS-induced colitis and showed that JTE907 treatment induced CD4 + CD25 + FoxP3 + cells in the lamina propria, which was associated with attenuation of colitis." (PMID 34298921, 2021). "The relevance of this distinction lies in the observation that intestinal inflammation can suppress Foxp3 expression in a mouse model of colitis, such that intestinal Foxp3+ Treg therein convert into pathogenic Th17 cells." (PMID 33777019, 2021). "TCDD was also shown to suppress colitis through the induction of Tregs while suppressing Th17 cells, and this was found to be associated with demethylation of CpG islands of FoxP3 and increased methylation in IL-17 promoter." (PMID 33105907, 2020).
colitis (continued). "Instead, the severe colitis was rather due to the fact that most RelA-deficient Tregs lost Foxp3 expression in the colon and mLN, potentially differentiating in pathogenic effector T cells." (PMID 31749798, 2019). "D– mice with fewer RORγt/FoxP3+ T reg cells were significantly more susceptible to colitis than D+ mice." (PMID 31417552, 2019). "Transfer of the cecal bacteria from D+ or D– mice to germfree recipients phenocopied the higher numbers of RORγt/FoxP3+ cells and reduced susceptibility to colitis in D+ vs. D– recipient mice." (PMID 31417552, 2019). "In contrast, recipient mice deficient in mPGES-1 exhibit more severe colitis that corresponds with a reduced capacity to generate FoxP3+ T cells, especially in mesenteric lymph nodes." (PMID 30619314, 2018). "In co-housed mice the acquisition of Rickenellaceae by Nod2+/+ mice was associated with increased CD4+ LAP+ Foxp3− proportion and less severe colitis." (PMID 30250234, 2018). "Alpinetin (30 mg/kg) up-regulated expression of miR-302, downregulated expression of DNMT-1, and promoted association of CREB and promoter region of Foxp3 in colons of colitis mice." (PMID 30166541, 2018). "Intestinal infections with the parasitic nematode H. polygyrus are known to expand CD4+ Foxp3+ Tregs and lead to chronic inflammation in susceptible mouse strains; two features that are considered to promote carcinogenesis in colitis-associated colon cancer." (PMID 28938014, 2017). "Taken together, these data support the idea that over-expression of CD200 in CD200tg mice enhances CCR4 dependent Foxp3+ Treg cell migration to the colon in mice to suppress a chronic inflammatory response associated with chronic DSS colitis." (PMID 26841120, 2016). "Similar to human IBD, a seemingly paradox increased mucosal infiltration of Foxp3+ T cells is associated with colitis in IL-10R blocked mice." (PMID 27611574, 2016). "Smad2/Smad3 double deficient mice develop fatal inflammatory diseases with reduction in Foxp3 expression in CD4+ T cells while Smad2 deficiency make mice susceptible to DSS induced colitis." (PMID 28003811, 2016). "In contrast, DSS-induced colitis was associated with a significantly reduced percentage of Foxp3+ lymphocytes within the LP and B. infantis feeding partially reversed the drop in Foxp3+ lymphocytes within the LP." (PMID 23704880, 2013). "We found that the administration of DTx between days 14 and 18, leading to the deletion of Foxp3+ Treg, resulted in an immediate weight loss of mice representing the onset of colitis." (PMID 22849659, 2012). "WF's protection against colitis associated with a microbiota-dependent increase in Foxp3+ T-cells (Tregs), which could be recapitulated in vitro." (PMID 41443299, 2025). "Since the reduced colitis severity was associated with a shift of CD4+ T-cell infiltration towards Foxp3+ Treg cells, we hypothesised that Foxp3+ Treg cells contribute to the limitation of colonic inflammation." (PMID 38839272, 2024). "Thus, sclerosing cholangitis attenuates colitis severity in mouse models and is associated with an increased colonic Foxp3+ Treg-cell frequency." (PMID 38839272, 2024). "Our results showed that the increased mRNA level of FOXP3 in colitis tissues may be associated with significantly upregulated Arg-1." (PMID 36713833, 2023). "In addition, in a T cell transfer model of colitis, Aim2−/−-naïve T cells induced less severe body weight loss and displayed a higher ability to differentiate into FOXP3+ cells in vivo." (PMID 35216346, 2022). "Anti-inflammatory function of these cells is associated with a transcription factor called FOXP3, but PORγ expression including anti-inflammatory and colitis preventative properties, along with FOXP3 seem to increase Immunosuppressive properties of these cells." (PMID 35410210, 2022).
colitis (continued). "This has been further demonstrated by a study in which both FOXP3+ Tregs and Tr1 cells control Th17-mediated colitis in an IL-10-dependent manner as pathogenic Th17 cells expressing a dominant negative form of the IL-10 receptor were unresponsive to IL-10-mediated suppression." (PMID 36389662, 2022). "In addition, epithelial PBLD deficiency in TNBS-induced colitis was associated with decreased CD4+ Foxp3+ cells (a marker of T regulatory cells) and increased IL-17A+ cells." (PMID 34059646, 2021). "Third, TLR/MyD88 signaling in mTECs is important for the proper development of thymic CD73–CD25+Foxp3+ Tregs since its abrogation resulted in a decreased number and the functionality of Tregs, associated with pathological effects in the mouse model of colitis." (PMID 32398640, 2020). "QCHS and SASP significantly reduced the Th17/Treg ratio in the experimental colitis mice and downregulated the levels of the Th17 cell-associated cytokine IL-17 and increased the levels of the Treg-associated cytokine IL-10 and transcription factor Foxp3." (PMID 32967687, 2020). "In these mice, colitis is associated with expansion of T helper type 1 (Th1) and Th17 cell populations and a decrease in the number of FoxP3+ regulatory T (Treg) cells, and the pathology is linked to the inability of intestinal Cnb1-deficient CD11chighMHCII+ cells to express IL-2." (PMID 29549257, 2018). "suggests that IL-33 treatment could protect against the TNBS-induced colitis by enhancing Foxp3 expression associated with Treg functions." (PMID 24491821, 2014). "In addition, cooperation between iTreg and nTreg cells appears to be required for protection from the autoimmune disease that develops in Foxp3-deficient mice 133, and protection from colitis induced by transfer of naive CD4+ T cells." (PMID 23405904, 2013). "To determine whether the Mst1 deficiency altered Foxp3+ Treg cell functions, we employed the experimental colitis model induced by adoptive transfer of naïve T cells into Rag2-/- mice." (PMID 24040101, 2013). "In contrast, pioglitazone-treated mice not only recovered from colitis and its associated weight loss, but also showed a switch from a predominant Th17 into an iTreg phenotype characterized by increased expression of FOXP3 and decreased IL17-A and RORγt in CD4+ T cells of the colonic LP and MLN." (PMID 23592971, 2013). "We examined whether a defect in CD4+FoxP3+ regulatory T cells (Treg) underpins the pathogenesis of colitis in the Gαi2−/− (Gαi2-deficient) colitis model." (PMID 21966415, 2011). "Thus Gpr83-deficient mice had normal frequencies of CD4+ Foxp3+ cells in the primary and secondary lymphoid organs and these cells retained their suppressive activity in vivo in a T-cell transfer model of colitis." (PMID 18479351, 2008). "In addition, although the results indicate a potential association among Foxp3 upregulation, microbiota alterations, and reduced colitis severity in maternal mice, the precise molecular and cellular mechanisms mediating these effects remain incompletely understood." (PMID 40713878, 2025). "The expressions of Foxp3 and retinoic orphan receptor gamma T (RORγt) in colonic tissue were both positively associated with A. muciniphila colonization, and A. muciniphila administration markedly promoted colonic RORγt+ Treg cell responses to ameliorate colitis." (PMID 36835655, 2023). "Furthermore, we have recently found that endoscopic administration of eASCs in the colon submucosa of TNBS-colitic rats attenuated the severity of colitis and reduced inflammation, which was associated to increased expression of Foxp3 and IL−10 mRNA in mLNs of eASC-treated rats." (PMID 29937494, 2018). "Examples where chronic inflammation may support iTreg development include mouse models of asthma, colitis that occurs during T cell expansion in a lymphopenic environment, adoptive transfer immunotherapy for the treatment of Foxp3-deficiency, and infection with intestinal parasites." (PMID 23801990, 2013).
colitis (continued). "We found that the maternal mice infected with Emu exhibited significant resistance to colitis, characterized by increased expression of Foxp3 in colonic tissue." (PMID 40713878, 2025). "SCFAs promote Treg differentiation via HDAC9 inhibition-mediated FOXP3 upregulation and enhance FOXP3+ Treg function to suppress colitis." (PMID 41488637, 2025). "Kang and Kim (2016) found that LBP significantly inhibited Th17 cell differentiation and RORγt expression in the lamina propria of the colon and increased Treg cell differentiation and Foxp3 expression in a TCBS‐induced mouse colitis model." (PMID 40488195, 2025). "Our previous work also demonstrated that peroral administration of L. reuteri reduces pro-inflammatory CD11b+CD11c+ DCs in mesenteric lymph nodes (MLNs), key sources of inflammatory cytokines—while expanding Foxp3+CD4+ T cells during colitis." (PMID 40298818, 2025). "In murine colitis models, exogenous succinate promotes FOXP3 degradation to impair Treg-mediated immunosuppression, exacerbating inflammation." (PMID 41488637, 2025). "(H) Statistical analysis of the percentage CD4+ FOXP3+ Treg cell in the spleen, mesenteric lymph nodes, and colon 6 weeks after colitis induction (n = 5)." (PMID 40183773, 2025). "The expression of forkhead box P3+ (FOXP3+) regulatory T cells (Tregs) was measured by flow cytometry and immunohistochemical assay in colitis model and patient cohort." (PMID 40309194, 2025). "RT-qPCR analysis of splenic tissue revealed a modest reduction in Foxp3 expression in ERAP1+/− colitis mice compared with ERAP1+/− controls (p < 0.05), which persisted even after sulfasalazine treatment." (PMID 40977735, 2025). "Its colonization can augment Foxp3/RORγt regulatory T cells (Treg cells) and induce IL-10 production, thereby mitigating colitis in mice." (PMID 39408951, 2024). "Foxp3+ regulatory T cells (Tregs) play a vital role in suppressing IL-23 expression and the development of colitis." (PMID 39379604, 2024). "In Foxp3-/- mice with experimental colitis, iTr35 cells, like nTreg cells, restored the homeostasis of the immune system, suppressed T cell proliferation, and prevented the development of colitis." (PMID 38386086, 2024). "To determine the significance of Sirtuins to Treg biology in colitis, we induced colitis in Foxp3‐tdTomato‐IL17‐EGFP mice with DSS." (PMID 38415949, 2024). "For instance, HIF-1α–dependent induction of FoxP3 enhanced anti-inflammatory effect of regulatory T cells and protected against T-cell–mediated colitis." (PMID 39585307, 2024). "In the present study, we also found that the colitis mice presented similar results with lower frequencies of mTreg (CD4+Foxp3+, CD4+CCR7+Foxp3+, CD4+CCR7−Foxp3+) cells and higher mTh17 (CD4+CCR6+, CD4+CCR7+CCR6+, CD4+CCR7−CCR6+) cells." (PMID 38202824, 2024). "It was observed that OA inhibited DSS-induced colitis in Th17 cells by suppressing the expression of IL-1, NF-ĸB, MAPK, and RORγt, as well as by inducing the expression of FOXP3, IL-10, and myeloperoxidase, effectively blocking the colitis process." (PMID 39064870, 2024). "Only Foxp3 was upregulated by MSC treatments in Winnie mice and chemically-induced colitis, which is predominately expressed by Tregs, which are a FOXP3 expressing immune cell population." (PMID 38503815, 2024). "Clusters IV and XIVa of the genus Clostridium improve IBD in a colitis model through inducing Treg cells and increasing Foxp3 transcription factor expression." (PMID 38404289, 2024). "We found a convergence of Relb∆CD11c and Nfkb2∆CD11c mice with respect to immune phenotypes—they both accumulated FoxP3+ Tregs in the intestine and were resilient to experimental colitis." (PMID 39060515, 2024). "Taken together, the protective effect of sclerosing cholangitis on colitis appears to be dependent on the presence of Foxp3+ Treg cells." (PMID 38839272, 2024).